CTSD (cathepsin D)
Description:
Acid protease active in intracellular protein breakdown. Plays a role in APP processing following cleavage and activation by ADAM30 which leads to APP degradation. Involved in the pathogenesis of several diseases such as breast cancer and possibly Alzheimer disease.
Synonyms: CPSD; CLN10; HEL-S-130P
Tractability: Small molecule: a structure with a bound ligand is known; a high-quality ligand is known; it has a high-quality binding pocket; it belongs to a druggable protein family. Antibody: its Gene Ontology location is reachable by antibodies, with high confidence; UniProt places it where antibodies can reach, with medium confidence; UniProt predicts a signal peptide or a membrane-spanning region. PROTAC: ubiquitination databases record sites on it; its protein half-life has been measured; a small molecule that binds it is known.
Target class: Aspartic protease; Aspartic protease A1A subfamily; Protease; Enzyme; Aspartic protease AA clan
Chemical probes: PD081969, PD083502
Safety:
Unwanted effects reported when the protein is acted on. In parentheses: how it was acted on, where the effect was seen, and who reports it.
retinal photoreceptor degradation (inhibition; ocular; source: Brennan et al. (2024))
Gene: Protein-coding gene on chromosome 11 (1,752,752 to 1,764,573, reverse strand). Ensembl gene ENSG00000117984.
Subcellular location: Lysosome; Melanosome; Secreted, extracellular space
Pathways (Reactome):
Immune System: MHC class II antigen presentation; Neutrophil degranulation
Signal Transduction: Estrogen-dependent gene expression; Insulin receptor recycling
Extracellular matrix organization: Collagen degradation
Metabolism of proteins: Metabolism of Angiotensinogen to Angiotensins
Gene Ontology:
Molecular function: peptidase activity; protein binding; aspartic-type endopeptidase activity; aspartic-type peptidase activity; cysteine-type endopeptidase activity; endopeptidase activity; hydrolase activity
Biological process: execution phase of apoptosis; lipoprotein catabolic process; positive regulation of apoptotic process; proteolysis; regulation of establishment of protein localization; antigen processing and presentation of exogenous peptide antigen via MHC class II; insulin catabolic process; insulin receptor recycling
Cellular component: cytosol; endosome membrane; extracellular exosome; extracellular matrix; extracellular region; lysosomal membrane; lysosome; membrane raft; ficolin-1-rich granule lumen; lysosomal lumen; specific granule lumen; tertiary granule lumen; cytoplasm; endosome lumen; melanosome
Genetic constraint (gnomAD): Loss-of-function variants: 28 observed, 43.35 expected, observed/expected ratio (o/e) 0.65, 90% interval 0.48 to 0.89. The upper end of that interval is the gene's LOEUF score, 0.89, which puts it in group 3 of 6, group 1 being the genes least tolerant of losing a copy. Missense variants: 485 observed, 565.9 expected, observed/expected ratio (o/e) 0.86, 90% interval 0.8 to 0.92. Synonymous variants: 270 observed, 253.52 expected, observed/expected ratio (o/e) 1.07, 90% interval 0.96 to 1.18.
Gene-disease validity (ClinGen):
ClinGen rates the evidence that CTSD causes each of these diseases.
neuronal ceroid lipofuscinosis (autosomal recessive): Definitive.
Homologues: Orthologues: chimpanzee IFITM10 (98% identical), dog CTSD (88% identical), pig CTSD (88% identical), macaque CTSD (86% identical), rat Ctsd (82% identical), mouse Ctsd (81% identical), guinea pig CTSD (80% identical), tropical clawed frog ctsd (65% identical), zebrafish ctsd (64% identical), Caenorhabditis elegans asp-4 (53% identical), Drosophila melanogaster cathD (52% identical). Paralogues in human: NAPSA (46% identical), CTSE (44% identical), PGA3 (43% identical), PGA4 (43% identical), PGA5 (43% identical), REN (39% identical), PGC (37% identical), BACE1 (28% identical), BACE2 (26% identical).
Diseases named in the same sentence as CTSD in open-access papers:
CTSD is named in the same sentence as 298 diseases in open-access papers, as found by Europe PMC text mining. Sharing a sentence is not in itself a finding about the gene and the disease. The quoted sentences say what the papers report.
breast carcinoma (159 papers, 1989 to 2026). "In mammary epithelial cells, CTSD deficiency disrupts mTORC1 signalling and delays breast cancer progression." (PMID 40796615, 2025). "Cathepsin D deficiency can inhibit the development of breast cancer by blocking signal transduction mediated by the mTORC1 complex." (PMID 39944834, 2025). "Previous studies has linked cathepsins B, D, and L to breast cancer metastasis, and cathepsin D activity is known to be regulated by oestrogen." (PMID 39944834, 2025). "Cathepsin D expression significantly predicts poor prognosis in breast cancer and is associated with variables of poor prognosis and shorter outcome." (PMID 38578521, 2024). "Kaplan–Meier analysis showed that Cathepsin D expression was significantly associated with shorter breast cancer-specific survival (p = 0.001), higher risk of recurrence (p = 0.001) and distant metastasis (p < 0.0001)." (PMID 38578521, 2024). "CTSD is also associated with tumor progression, invasion, and metastasis in human malignancies, especially breast cancers, and is therefore a useful biomarker of breast cancer with poor prognosis." (PMID 37233475, 2023). "In a mouse model of breast cancer, CTSD deficiency in the mammary epithelium impairs mTORC1 signaling and triggers the appearance of vacuolated cells with reduced proliferative activity upon serum starvation." (PMID 35351824, 2022). "The CTSD gene, a member of the peptidase A1 family, has been shown to be highly expressed in the breast cancer tumor microenvironment and is strongly associated with the survival of breast cancer patients." (PMID 35892430, 2022). "Mutations in CTSD are associated with several human diseases including breast cancer, Alzheimer’s disease, Parkinson’s disease, and a subtype of NCL (Batten disease)." (PMID 33572113, 2021). "Mutations in HEXA cause Tay-Sachs disease, while mutations in CTSD are associated with breast cancer, Alzheimer’s disease, Parkinson’s disease, and a subtype of NCL called CLN10 disease." (PMID 33572113, 2021). "In summary, our data demonstrate that deficiency for a major lysosomal proteinase, i.e., CTSD, interferes with a dominant oncogenic signaling pathway in breast cancer, i.e., PI3K-mTOR signaling." (PMID 33046706, 2020). "Higher expression of CTSD has also been correlated with an increased risk of clinical metastasis and short survival of patients with breast cancer." (PMID 32244796, 2020). "Overexpression of cathepsin D has been associated with many types of cancers such as gastric carcinoma, melanoma, ovarian cancer and breast cancer." (PMID 30177970, 2018). "Another member, cathepsin D, has been associated with poor prognosis for breast cancer as a result of stimulation of breast cancer cell proliferation, fibroblast outgrowth, angiogenesis, breast tumor growth and metastasis formation." (PMID 28968398, 2017). "In this study, two read-through gene fusions (SCNN1A-TNFRSF1A and CTSD-IFITM10) were identified that were significantly associated with breast cancer." (PMID 26561834, 2015). "Others have also shown that overexpression of cathepsin D in human breast cancers is associated with a higher risk of relapse and metastasis." (PMID 22110952, 2011). "Overexpression of Cathepsin D has been associated with poorer outcome in breast carcinoma, although these findings have not consistently been replicated." (PMID 21063399, 2010). "MDA-MB-231, unlike MCF-7, are cells with high mobility and have been used, therefore, to monitor WEB-2086 effects on cell migration and cathepsin D levels which associate closely with breast cancer invasiveness." (PMID 16721373, 2006). "The results presented here on 2810 patients confirm that high cytosolic cathepsin-D values are associated with poor prognosis in human primary breast cancer." (PMID 9888472, 1999). "C-myc and c-erbB-2 amplification and/or overexpression as well as total cathepsin-D (CD) concentration have been reported to be associated with poor prognosis in breast cancer." (PMID 10604737, 1999).
breast carcinoma (continued). "We conclude that high stromal cell cathepsin D expression is associated with a poor short- and long-term outcome in breast cancer." (PMID 7819033, 1995). "High extracellular expression of CTSD is associated with metastasis in breast cancer." (PMID 36768435, 2023). "Likewise, the overexpression of MMP9 and CTSD observed in HMECs infected with HCMV-BL was associated with the most aggressive subtype of breast cancer, tumor cell invasion, and metastasis." (PMID 35003089, 2021). "As concerns cathepsin D, its high levels are significantly associated with the ER-positive and PgR-positive status of breast cancer, which might be expected as cathepsin D expression is under oestrogen control in ER-positive breast carcinomas." (PMID 33916398, 2021). "The protein–protein interaction networks indicated that the target proteins, including cathepsin D and B23, were mainly associated with cell differentiation and apoptosis, while the recurrence of breast cancer majorly led to uncontrolled proliferation triggered by oncogenes such as c-Myc." (PMID 32846884, 2020). "The lysosomal aspartic protease Cathepsin D (CTSD) is associated with breast cancer progression." (PMID 33046706, 2020). "Determination of CTSD status in breast cancer patients might help identify those with different risk levels of relapse." (PMID 26995190, 2016). "High cytosolic cathepsin D levels are associated with poor prognosis in primary breast cancer." (PMID 12698189, 2003). "In breast cancer, anti-cathepsin D therapy has been found to activate both innate and adaptive immunity, indicating that cathepsin D is a potential target for tumor immunotherapy." (PMID 39944834, 2025). "In breast cancer cells derived from murine MMTV-PyMT breast cancers, CTSD deficiency has been shown to block tumor cell proliferation and to enhance cellular quiescence by impairing mTORC1 signaling." (PMID 41185039, 2025). "In MCF−7 human breast cancer cells, the cathepsin D gene expression is regulated by multiple pathways." (PMID 40538803, 2025). "In breast cancer, CTSD and P2RX4 expression are correlated, where tumor and metastatic cells have much higher levels of CTSD in the ECM and P2RX4 expression compared to healthy neighboring cells." (PMID 41009609, 2025). "Recent studies have reported that CTSD enhances the invasion and metastasis of breast cancer by promoting liver proteinase-ubiquitin-proteasome degradation." (PMID 40861815, 2025). "In solid tumors, CTSD is required for the migration and invasion of gastric and breast cancer cells." (PMID 40796615, 2025). "The level of expression of Cathepsin D was correlated with oestrogen receptor status in breast cancer." (PMID 38578521, 2024). "Here, we also show that Cathepsin D is a prognostic marker within ER-positive patients, a group of breast cancer patients with relatively good prognosis." (PMID 38578521, 2024). "Immunohistochemical examination of breast carcinoma microarray sections revealed positive staining of Cathepsin D localized to the cytoplasm of invasive malignant cells." (PMID 38578521, 2024). "Cathepsin D expression in breast cancer correlates with HER2 status, warranting further investigation in larger, trastuzumab-treated patient cohorts to assess its potential as a predictor of treatment response." (PMID 38578521, 2024). "Our study found that 71.2% of breast cancer tissues displayed positive Cathepsin D expression using the cut-off of > 30% cytoplasmic staining." (PMID 38578521, 2024). "Further research is needed to confirm these findings and to explore the potential therapeutic implications of targeting Cathepsin D in breast cancer treatment." (PMID 38578521, 2024). "This study aimed to evaluate the expression and prognostic significance of Cathepsin D in early-stage breast cancer." (PMID 38578521, 2024). "CTSD and CTSB, two aspartic proteases, have been linked with tumourigenesis and worse therapy response in breast cancer and glioblastoma." (PMID 39187937, 2024).
breast carcinoma (continued). "For this reason, there is a great need to re-evaluate Cathepsin D significance in breast cancer addressing these issues in particular." (PMID 38578521, 2024). "SPRED2 appears to activate autophagy by interacting with selective autophagic components, such as LC3, p62, a neighbor of breast cancer susceptibility gene I (BRCA1) and cathepsin D, as evidenced by co-immunoprecipitation of these molecules with SPRED2." (PMID 38892460, 2024). "In conclusion, this large-scale study provides compelling evidence for the clinical relevance of Cathepsin D as a prognostic marker in breast cancer." (PMID 38578521, 2024). "Several approaches, such as immunohistochemistry and cytosolic immunoassay, have demonstrated that in most breast cancers, Cathepsin D is overexpressed 2- to 50-fold compared to its concentration in normal mammary gland cells." (PMID 38578521, 2024). "This study aimed to address the gap in the literature on the prognostic value of Cathepsin D expression in breast cancer patients." (PMID 38578521, 2024). "The coding gene ESR1 is a direct target of miR-301a-3p, and this interaction indirectly leads to the downregulation of CTSD expression in breast cancer." (PMID 38611021, 2024). "The results indicated that there was a significant increase in the CTSD gene expression levels in stages 3 and 4 for all patients with breast cancer." (PMID 39202273, 2024). "Importance of Cathepsin D in breast cancer was first emerged by the studies of proteins whose expression is regulated by oestrogen in breast cancer." (PMID 38578521, 2024). "Given the impact of changes in cathepsin D expression levels on breast cancer prognosis, we also determined its expression in control and resistant cells." (PMID 39339215, 2024). "This study found that hormone-sensitive breast cancer cell lines secreted a kind of estrogen-induced glycoprotein, which was later identified as a precursor of Cathepsin D." (PMID 39080685, 2024). "In breast cancer, a large number of studies have investigated Cathepsin D expression using either immunohistochemistry or measurement of cytosolic Cathepsin D content (by radiometric immunoassay (IRMA), ELISA or Western blot)." (PMID 38578521, 2024). "The level of CTSD expression was elevated in breast cancer tumors when compared to normal tissues, as demonstrated by the differential gene expression in clinical patients." (PMID 39202273, 2024). "Cathepsin D is a proteolytic enzyme that is normally localized in the lysosomes and is involved in the malignant progression of breast cancer." (PMID 38578521, 2024). "Cathepsin D is an aspartic endoproteinase in lysosome and is well known for its roles in angiogenesis, proliferation, and invasion in breast cancer." (PMID 38249992, 2024). "Cathepsin D is an aspartic endoproteinase that is localized in the lysosomes and extracellular matrix and is involved in the malignant progression of breast cancer." (PMID 38578521, 2024). "In agreement with this, cathepsin D expression was high in both breast cancer cell lines, i.e., MDA-MB-231 and SK-BR-3, with the signal of active cathepsin D being highest in SK-BR-3." (PMID 37896224, 2023). "Anantaraju (2016) identified several small-molecule inhibitors that blocked CTSD activity and inhibited breast cancer cell growth." (PMID 36768435, 2023). "This latter has been exemplified with the abundance of CTSD-IFITM10 readthrough fusions during breast cancer cell proliferation." (PMID 35151276, 2022). "Induces apoptosis via cathepsin D accumulation and enhances vorinostat-mediated cell death in breast cancer models." (PMID 34967891, 2022). "For instance, Cathepsin D (CTSD) is a lysosomal protease marker that has shown fewer prognoses in human breast cancer by blocking tumor development in cell- independent way." (PMID 35419411, 2022). "The autophagy inhibitor, lucathone, impairs autophagic degradation and induces apoptotic cell death in breast cancer cells by stimulating the expression of CTSD." (PMID 35252181, 2022).